GCG (glucagon)
Diseases named in the same sentence as GCG in open-access papers (continued):
Sharing a sentence is not in itself a finding about the gene and the disease.
Insulin resistance (continued). "The ELAVL1 gene in MDD patients was also found to be enriched in pathways such as cellular senescence, adipocytokine signaling pathway, glucagon signaling pathway, and insulin resistance, indicating its association with metabolic disorders in depressive patients." (PMID 38714976, 2024). "In addition glucagon activated hepatic lipolysis which lower hepatic lipids, a condition known to be associated with insulin resistance." (PMID 39114126, 2024). "We previously observed that glucagon resistance and insulin resistance may coexist but importantly also occur independently of each other, highlighting the differential pathophysiological mechanisms underlying glucagon and insulin resistance." (PMID 38705923, 2024). "Insulin resistance of alpha cells may decrease the inhibitory effects of insulin on glucagon secretion; additionally, loss of beta-cell mass could decrease local levels of insulin in the fed state." (PMID 38579751, 2024). "Potential mechanisms underlying the association between smoking and MAFLD may be related to insulin resistance, hyperinsulinemia, dyslipidemia, hepatic steatosis, inflammation, and elevated catecholamine and glucagon levels." (PMID 38654043, 2024). "In addition to impaired glucose control and insulin resistance, pancreatic beta cell loss and impaired insulin, and glucagon production secreted hallmark T2D." (PMID 36077198, 2022). "The liver fat also causes insulin resistance, and the combined impairment of the actions of glucagon on amino acid metabolism in the liver, while its effect on glucose production are preserved, and the insulin resistance, probably are responsible for the fasting hyperglycemia in T2DM." (PMID 35990325, 2022). "However, insulin resistance in T2D and its deficiency in T1D seem to have differing effects on plasma glucagon levels and their relationships to hepatic AC/cAMP activity." (PMID 35569125, 2022). "We hypothesised that the glucagon–alanine index, an indicator of the functional integrity of the liver–alpha cell axis, would associate with liver fat and insulin resistance in our cohort of women with low levels of liver fat." (PMID 33275161, 2021). "Furthermore, our data indicates an insulin-resistance-independent association of liver fat content with the glucagon–alanine index." (PMID 33275161, 2021). "The reason for the elevated insulin level with moderately increased glucose levels is not known, but could be linked to an enhanced activity of beta cells associated with a degree of peripheral insulin resistance or to a modification of glucagon secretion." (PMID 29795582, 2018). "Interestingly, increased branched-chain amino acids can promote insulin resistance and thus may be related to insulin resistance associated with mild increases in glucagon." (PMID 38814331, 2024). "The underlying mechanisms behind the association between smoking and NAFLD may related to insulin resistance, hyperinsulinemia, dyslipidemia, hepatic steatosis, inflammation, and increased levels of catecholamine and glucagon, which can be induced by long-term smoking and nicotine use." (PMID 35488966, 2022). "In IST-Cell, 14 miRNAs, such as those involved in endocrine resistance, insulin resistance, and insulin and glucagon signaling, were upregulate HBERs." (PMID 40549708, 2025). "In the present study, the results showed that TA can reduce glucagon levels in αTC1-6 cells, which is probably related to that TA improved autophagy activity and insulin resistance by inhibiting PI3K/AKT signaling pathway." (PMID 41150819, 2025). "The miR-320a has been reported to inhibit glucagon secretion, and to be negatively correlated with fasting plasma glucose and insulin resistance in obese individuals with metabolic syndrome." (PMID 41282288, 2025). "It has the function of enhancing GLu‐dependent insulin secretion, inhibiting glucagon secretion, slowing gastric emptying to reduce blood GLu, and alleviating insulin resistance." (PMID 40078029, 2025).
Insulin resistance (continued). "In NAFLD, dysregulation of the glucagon signaling pathway is a key pathological factor, especially in the context of insulin resistance." (PMID 39948335, 2025). "According to KEGG pathway enrichment, pyruvate metabolism, lipid and atherosclerosis, insulin signaling pathway, fatty acid biosynthesis, bile secretion, glucagon signaling pathway, and insulin resistance were involved." (PMID 40989883, 2025). "These top 5 hub genes are involved in the longevity related pathway, glucagon signaling pathway, insulin resistance pathway and Alzheimer disease pathway." (PMID 40642087, 2025). "Physiologically, SGLT2 inhibitors seem to have hepatoprotective impact, including the reduction of oxidative stress, glucagon-driven hepatic lipogenesis, systemic inflammation, and insulin resistance in addition to enhancing glycemic control." (PMID 41157142, 2025). "Studies have suggested that excess THs raise blood glucose levels through several pathways, including stimulating glucagon secretion, increasing gluconeogenesis and glycogenolysis and inducing insulin resistance in the liver and peripheral tissues." (PMID 40193316, 2025). "Pancreatic hormones, including insulin and glucagon, show improved β-cell function and insulin sensitivity, reflected in decreased homeostasis model assessment insulin resistance (HOMA-IR)." (PMID 41155711, 2025). "After 21 days of treatment with STZ, serum insulin and glucagon concentrations were measured to assess insulin resistance in all animals." (PMID 41463431, 2025). "To identify factors involved in the increases in glucagon, we first determined correlations with anthropometric parameters and insulin resistance measured as HOMA-IR." (PMID 39599691, 2024). "BCG vaccination significantly improved changes in fasting glucose and insulin levels, insulin resistance indexes, and glucagon-to-insulin ratios in conjunction with the HFD at the end of the experiment." (PMID 38929483, 2024). "It indicated that metabolites with high abundance in rest and wake participated in the same process of Insulin resistance, and the high abundance metabolites detected in sleep were involved in the Glucagon signaling pathway." (PMID 39337348, 2024). "In multilinear regressions, insulin resistance was the strongest predictor of elevated hypoglycemic responses of glucagon, cortisol, and ACTH." (PMID 37708362, 2024). "paracasei NL41 for 12 weeks reduced insulin resistance, HbA1c, glucagon, leptin, and oxidative stress." (PMID 39125375, 2024). "Previous studies have reported that IL-6 can promote glucagon secretion and induce insulin resistance." (PMID 36769472, 2023). "Gut bacteria in T2DM elevated insulin resistance by decreasing insulin signaling and increasing glucagon signaling." (PMID 37298483, 2023). "Large quantity of replicated HBV in host will cause inflammatory necrosis of hepatocytes resulting in the reduced inactivation of insulin and glucagon, which will lead to impaired glucose tolerance and insulin resistance." (PMID 37077357, 2023). "Function-loss experiments have proved that PTEN participates in the regulation of circulating glucagon levels and insulin resistance in HFD-fed mice." (PMID 36980960, 2023). "The relative TAG decreases in the liver of fed KD mice indicate insulin resistance, the increase in the glucagon/insulin ratio, and/or the increase in RA." (PMID 37011860, 2023). "Somatostatin analogs of the first generation reduce insulin resistance but also the pancreatic secretion of insulin and glucagon." (PMID 37628857, 2023). "These ARRDC4KO mice also showed insulin resistance along with glucagon resistance, both of which contribute to defective glucose homeostasis in diabetic states." (PMID 37451484, 2023). "GLP1R, GNAS, and GCG were related to insulin resistance, which were verified by the previous studies." (PMID 36686441, 2022).
Insulin resistance (continued). "Several pathways are noteworthy, such as MicroRNAs in cancer, Insulin resistance, Glucagon signaling pathway, and Glutamater synapse." (PMID 36105406, 2022). "The second study’s objective was to determine how the hyperresponsiveness of the beta cell and the insulin resistance in youth compared to adults (both with IGT or T2D) was due to an increased glucagon release." (PMID 36686477, 2022). "Changes in BW, blood pressure (BP), BGL, water and food consumption, serum insulin, serum glucagon and insulin resistance (IR) were monitored." (PMID 35265127, 2022). "Growing leucine intake can enhance glucose metabolism, decrease the insulin resistance induced by diets, and lower levels of plasma glucagon and the expression of hepatic glucose 6 phosphatase, which is the key enzyme for regulating hepatic glucose production." (PMID 36034924, 2022). "The alphaIRS1KO mice showed impaired glucose tolerance, insulin resistance, and inadequate suppression of glucagon secretion following glucose administration." (PMID 33839150, 2021). "Elevated insulin and glucagon are hallmarks of β-cell stress and insulin resistance, and NGOB mice showed clear β-cell compensation, with a robust increase in IGR that was lost in the T2D cohort." (PMID 33467110, 2021). "The release of major stress and steroid hormones, catecholamine overload, and glucagon all participate in generating a state of insulin resistance with increased hepatic glucose output and glycogen breakdown." (PMID 33463901, 2021). "T2DM is characterized by changes in beta-cell mass, decreased insulin secretion, and elevation in intestinal glucose absorption, upsurge in glucagon secretion, increase in insulin breakdown, insulin resistance, and increased levels of catecholamines." (PMID 35106234, 2021). "After poor sleep quality, the sympathetic nervous system is overactivated, which in turn leads to insulin resistance and aberrant glucagon secretion." (PMID 34556157, 2021). "Acute infections also lead to increased insulin resistance through enhanced secretion of the counter-regulatory hormones cortisol, glucagon and growth hormone." (PMID 33992101, 2021). "To further explore the insulin resistance defects, we examined glucagon responses following insulin injection during the insulin tolerance tests in the two individual knockouts." (PMID 33839150, 2021). "In obese mice, during insulin resistance, glucagon is increased and results in the release of higher levels of calcium, which induces calcium signaling leading to induction of higher insulin signaling." (PMID 32899471, 2020). "Similar to prediabetes subjects, overweight subjects had insulin resistance and significantly elevated levels of C-peptide, adiponectin and glucagon and lower level of ghrelin." (PMID 31941993, 2020). "The insulin resistance leads to an increase in the secretion of glucagon, breakdown of lipids and increased the re-absorption of glucose from nephrons." (PMID 32815547, 2020). "Propionate supplied in food has been shown to initiate metabolic events leading to increased glucagon levels in humans, and chronic consumption lead to weight gain and insulin resistance in mice." (PMID 32499766, 2020). "Glucose homeostasis is maintained by insulin and glucagon, whereas disrupted pancreatic islet functions and insulin resistance in T2D leads to glucose intolerance." (PMID 33192521, 2020). "In HFD-induced NAFLD mice, treatment with a dual GLP-1/glucagon co-agonist for 40 weeks prevented body weight gain, glucose intolerance and insulin resistance, while it decreased circulating and hepatic lipid content." (PMID 32823659, 2020). "Our work focused on the role of glucagon secretion and pancreatic α-cell function during insulin resistance states specifically induced by statin exposure." (PMID 31546230, 2019). "SIH is characterized by insulin resistance and an excess of the counterbalancing hormones of insulin, including glucagon, catecholamines, cortisol, and growth hormone." (PMID 30908518, 2019).
Insulin resistance (continued). "In recent years, insulin resistance in pancreatic α cells has been proposed; moreover, the relationship between insulin and glucagon has been gaining considerable attention." (PMID 31357734, 2019). "If insulin resistance is present in pancreatic α cells, these insulin signals are attenuated and affect glucagon secretion." (PMID 31357734, 2019). "From the KEGG pathway analysis in the current study, the glucagon signalling pathway, insulin resistance and insulin signalling pathway were found to be significantly associated with the DEGs between the two pig breeds." (PMID 31501489, 2019). "Insulin levels are higher than normal, but inadequate to overcome insulin resistance due initially to inappropriate glucagon secretion and to the lipo-toxicity that is characterized by greater triacylglycerol storage in non-fat tissues." (PMID 31781045, 2019). "We investigated glucagon suppression and its relationship with insulin resistance in prediabetic subjects undergoing atorvastatin therapy; in addition, we studied molecular insulin signaling in pancreatic α-cells exposed to atorvastatin in vitro." (PMID 31546230, 2019). "The correlation between α-cell mass and body weight we observed in control subjects is consistent with the recently described increased fasting plasma glucagon concentration observed in subjects with insulin resistance." (PMID 29352311, 2018). "Increased adipose lipolysis can induce ectopic fat deposits, and fat accumulation in muscle is shown to induce insulin resistance, while hepatic fat deposition enhances glucagon response to increase glucose output." (PMID 29410630, 2018). "We detected transcription factors CTCF, CTCFL, and Egr1 binding to the genomic region overlapping the differentially methylated CpG within EML3 gene; out of these, CTCF is proved to mediate glucagon production and Egr1 is responsible for insulin resistance." (PMID 30545422, 2018). "Previous studies revealed that glucagon-GLP-1 dual-agonist ZP2495 was superior compared with glucagon alone in the improvement of cardiac function in subjects with insulin resistance (IR)." (PMID 29576852, 2018). "We determined the serum insulin and glucagon levels by ELISA kits and calculated insulin resistance index (HOME-IR)." (PMID 29862294, 2018). "Upregulated genes in Aa-administrated mice were enriched for glucagon signaling pathway, adipocytokine signaling pathway and insulin resistance." (PMID 29066788, 2017). "Based on KEGG pathway analysis for differentially expressed genes in the liver of normal chow diet feeding mice, we focused on glucagon signaling pathway, adipocytokine signaling pathway, and insulin resistance." (PMID 29066788, 2017). "Despite the possible involvement of the GNDPA2, TMEM18, and ADCY3 loci in insulin resistance, insulin/glucagon regulation, and insulin secretion, respectively, we chose to retain them in the IV analysis." (PMID 28763444, 2017). "Those authors reported that leucine supplementation decreases glucose metabolism, reduces diet-induced insulin resistance and lowers plasma glucagon levels and hepatic glucose-6-phosphatase mRNA expression in rats." (PMID 28558680, 2017). "KEGG pathway analysis in liver microarrays suggested the induction of metabolic disorders, such as enrichment of glucagon signaling pathway, insulin resistance and adipocytokine signaling pathway, following A. actinomycetemcomitans administration." (PMID 29066788, 2017). "It is necessary to bring the glucagon pathway into consideration, in order to understand selective insulin resistance in the context of prediabetes progression." (PMID 29118381, 2017). "In humans, increased circulating concentration of glucagon is an indicator of insulin resistance and diabetic status." (PMID 28376869, 2017).
Insulin resistance (continued). "Taken together, these data are consistent with the premise that WD-fed mice display features of insulin resistance (e.g., islet mass expansion), while islets from db/db mice display features of T2D (e.g., elevated glucagon and indicators of dedifferentiation)." (PMID 29038790, 2017). "Glucocorticoids exert well-characterized effects on metabolism, including permissive effects on glucagon and inhibition of insulin action that result in impaired peripheral glucose uptake and insulin resistance." (PMID 27037194, 2016). "Based on these results, we conclude that obese, non-diabetic subjects can be metabolically characterized by elevated fasting glucagon levels, as well as hyperinsulinemia and insulin resistance." (PMID 26942445, 2016). "In fact, serum concentration of IGFBP‐1, unlike IGFBP‐3 which binds 75–90% of circulating IGF‐I, is heavily influenced by the metabolic (i.e., insulin resistance, and insulin and glucagon levels) and nutritional (fasting and refeeding) state of the individual." (PMID 26443692, 2016). "We suggest that the glucagon-cAMP-GSH axis is a potential therapeutic target to address insulin resistance in pathological conditions." (PMID 25961284, 2015). "The main hormonal and metabolic abnormalities in T2D are dysfunctional insulin secretion, glucagon excess, and insulin resistance, eventually beta-cell failure and defects in glucagon-like peptide-1 (GLP-1) secretory responses." (PMID 24400077, 2014). "The AVP system has also been suggested to contribute to insulin resistance and DM potentially through a variety of mechanisms including stimulation of glucagon and ACTH secretion and glycogenolysis, etc.." (PMID 24628831, 2014). "Beta-cell dysfunction, insulin resistance and impaired suppression of glucagon are key pathologic defects in type 2 diabetes (T2DM), partially dependent on the reduced incretin effect." (PMID 25285158, 2014). "Because the link between FGF21, adiponectin, glucagon, and insulin resistance is very strong, future studies should consider measurements of FGF21 in dolphins." (PMID 24065958, 2013). "Insulin resistance in sepsis is due to a decreased effect of insulin, but also reflects an imbalance between insulin and its counter-regulatory hormones (cortisol, glucagon, growth hormone, and catecholamines)." (PMID 23999826, 2013). "This was accompanied by significantly increased glucose, insulin and glucagon levels and the related gene expressions, all of which indicated possible insulin resistance." (PMID 24349075, 2013). "Together, these findings suggest that MASLD in T1D cannot be fully explained by insulin resistance alone and is likely to result from a combination of unique factors, including insulin delivery patterns, glucagon dysregulation, autoimmune effects, and ectopic fat metabolism." (PMID 40807122, 2025). "Therefore, TA directly inhibits glucagon secretion and improves insulin resistance, and indirectly regulates glucagon secretion and function, both of which are beneficial to the treatment of GCGN." (PMID 41150819, 2025). "Although insulin, glucagon, HbA1c, and C-peptide levels remained comparable between groups, insulin resistance, as measured by HOMA-IR, increased in the Placebo group but remained unchanged in the Citrus Flavonoids group, supporting a positive metabolic effect." (PMID 40904779, 2025). "While insulin resistance appears to play a role, additional factors—such as altered hepatic insulin signaling, glucagon dominance, adipose tissue dysfunction, and autoimmune inflammation—may contribute in this setting." (PMID 40807122, 2025). "The authors propose that individuals with well-controlled T1D may maintain normal hepatic glycogen stores and preserve a physiological glucagon-to-insulin ratio, which could protect against both insulin resistance and MASLD development." (PMID 40807122, 2025).